RALB (RAS like proto-oncogene B)
Diseases named in the same sentence as RALB in open-access papers (continued):
Sharing a sentence is not in itself a finding about the gene and the disease.
triple-negative breast carcinoma (2 papers, 2018 to 2021). An invasive breast carcinoma which is negative for expression of estrogen receptor (ER), progesterone receptor (PR), and human epidermal growth factor receptor 2 (HER2). "Consistent with this hypothesis, RalB silencing was able to impair invasion (by Transwell invasion assay) of two triple-negative breast cancer cell lines: MDA-MB-231 (carrying the KRasG13D mutation) and BT549 (Ras wild-type)." (PMID 30320548, 2018).
Arterial thrombosis (1 paper, 2025). The formation of a blood clot inside an artery. "Genetic deletion of Ral GTPases, RalA and RalB, conditionally in mouse platelets (RalAB double knockout [DKO]), results in a near complete defect in P-selectin externalization upon activation, while other platelet activation responses and arterial thrombosis are preserved." (PMID 39454881, 2025).
astrocytoma (1 paper, 2022). "Primary GBM cells show increased amounts of RalB protein in comparison with primary astrocytoma cells." (PMID 35897776, 2022). "Most of the GBM samples showed increased RalB levels compared to the low-grade astrocytoma samples." (PMID 35897776, 2022). "First, we have analyzed the expression levels of RalA and RalB proteins in primary cultures obtained from human GBM and grade II astrocytoma biopsies." (PMID 35897776, 2022). "A predominant expression of RalB in GBM samples is consistent with the data included in the GlioVis database (TCGA LGG_GBM dataset) and showed that transcriptional expression of RalB clearly increases in GBM samples in comparison with astrocytoma." (PMID 35897776, 2022).
bladder tumor (1 paper, 2022). "Note that the knock-out of either RalA or RalB does not affect the growth of mouse embryonic fibroblasts (MEFs), and slightly reduces the growth of some cancer cells, such as bladder tumor cells, when growing in low-serum conditions." (PMID 35897776, 2022).
Breast hypertrophy (1 paper, 2025). The presence of hypertrophy of the breast. "In this study, we performed a comprehensive cross-tissue TWAS integrating GTEx eQTL data with FinnGen GWAS summary statistics, identifying RALB as a robust candidate gene causally associated with breast hypertrophy." (PMID 41239602, 2025). "In conclusion, through an integrative TWAS framework, we identified RALB as a promising causal gene in the genetic architecture of breast hypertrophy." (PMID 41239602, 2025). "A two-sample Mendelian randomization (MR) analysis was conducted to investigate the potential causal effect of RALB expression on breast hypertrophy." (PMID 41239602, 2025). "Our integrative genomic analyses identified RALB as a robust susceptibility gene for breast hypertrophy." (PMID 41239602, 2025). "In whole blood, the susceptibility gene RALB, located at 2q14.3, showed strong evidence of colocalization with signals associated with breast hypertrophy." (PMID 41239602, 2025). "Mendelian randomization confirmed a significant causal relationship between elevated RALB expression and increased risk of breast hypertrophy (odds ratio = 1.26; 95% confidence interval: 1.17–1.35; P < .001)." (PMID 41239602, 2025). "The MR results revealed a significant positive causal association between increased RALB expression and the risk of breast hypertrophy (P < .001; odds ratio = 1.26; 95% confidence interval: 1.17–1.35)." (PMID 41239602, 2025). "Drawing on convergent lines of evidence, we nominate RALB as a plausible effector gene for breast hypertrophy." (PMID 41239602, 2025). "This analysis integrated eQTL data for RALB from whole blood with GWAS summary statistics for breast hypertrophy." (PMID 41239602, 2025). "Among these, RALB demonstrated the highest causal probability, with a PIP of 0.98 in GTEx whole blood, suggesting a strong likelihood of causal involvement in breast hypertrophy pathogenesis." (PMID 41239602, 2025).
breast invasive carcinoma (1 paper, 2021). "(a) Kaplan-Meier curve, obtained from TCGA 1097 cohort, showing the survival probability of patients with tumor breast invasive carcinoma having high or low RalA (pvalue: 5.15 e-03; pAdj: 1.35e-01) or RalB (pvalue: 1.77 e-05; pAdj: 5.99e-03) expression levels." (PMID 33404012, 2021).
cardiac hypertrophy (1 paper, 2025). "There have been advances in RALB in cardiovascular disease; for example, RALB is required for autophagy in mTOR-dependent cardiomyocytes, and RALB-associated RalGDS-mediated autophagy induction and exocyst function is critical for load-induced cardiac hypertrophy." (PMID 41398523, 2025).
cervical cancer (1 paper, 2020). A primary or metastatic malignant neoplasm involving the cervix. "The activation of RalB promoted the formation of starvation-induced autophagosome in cervical cancer HeLa cells and in immortalized bronchial epithelial HBEC3-KT cells." (PMID 32577124, 2020).
cyst (1 paper, 2021). A sac-like closed membranous structure that may be empty or contain fluid or amorphous material. "Despite RALB-shRNA-expressing cysts having a smaller size, the number of cells/cyst cross section was similar to the control, indicating that the smaller size was due to the absence of a lumenal space." (PMID 34815476, 2021).
glioblastoma (1 paper, 2022). The most malignant astrocytic tumor (WHO grade IV). "We have not detected caspase 3 cleavage, suggesting that the effect of RalB downregulation in primary glioblastoma cells does not trigger an apoptotic response." (PMID 35897776, 2022).
glioma (1 paper, 2022). A benign or malignant brain and spinal cord tumor that arises from glial cells (astrocytes, oligodendrocytes, ependymal cells). "In contrast, the heterozygosis loss of RALB improved the long-term survival of glioma patients." (PMID 35897776, 2022).
in situ carcinoma (1 paper, 2018). A malignant epithelial neoplasm which is confined to the epithelial layer without evidence of further tissue invasion. "(A) Quantitative analysis of RalB protein level in patient samples of normal juxtatumural tissue (n = 298), in situ carcinoma (n = 101), invasive ductal carcinoma (n = 439) and lymph node metastasis (n = 91)." (PMID 30320548, 2018).
insulinoma (1 paper, 2009). "Low levels of RalB were detected in insulinoma cell lines but not in freshly isolated pancreatic islets and may be the consequence of oncogenic transformation." (PMID 19890390, 2009).
intestinal tumors (1 paper, 2024). "Furthermore, compared to the B.a + PBS group, the B.a + rALB group showed a remarkable increase in the number and size of intestinal tumors." (PMID 39096436, 2024).
invasive ductal carcinoma (1 paper, 2018). "In invasive ductal carcinoma, RalB protein expression was slightly higher in luminal A and B than in HER2 +and triple-negative (TN) tumors, while RalA protein expression was slightly lower in TN tumors as compared to the other subtypes." (PMID 30320548, 2018).
laryngeal carcinoma (1 paper, 2020). Carcinoma that arises from the laryngeal epithelium. "The mechanism of DHA in regulating the crosstalk between IFI16 inflammasome and autophagy by inhibiting RalB expression was analyzed in order to provide clues for new therapeutic methods in laryngeal cancer." (PMID 32577124, 2020). "According to the results of the previous work, the mechanism of DHA in regulating the crosstalk between IFI16 inflammasome and autophagy by inhibiting RalB expression was analyzed in order to provide clues for new therapeutic methods in laryngeal cancer." (PMID 32577124, 2020). "Therefore, it is proposed that DHA may act as a RalB inhibitor and definite anticancer strategy needs further investigations in laryngeal cancer." (PMID 32577124, 2020).
leukemia (1 paper, 2016). A malignant (clonal) hematologic disorder, involving hematopoietic stem cells and characterized by the presence of primitive or atypical myeloid or lymphoid cells in the bone marrow and the blood. "To investigate this hypothesis, we genetically disrupted RALB signaling in human leukemia cells." (PMID 27556501, 2016).
myeloid leukemia (1 paper, 2014). A clonal proliferation of myeloid cells and their precursors in the bone marrow, peripheral blood, and spleen. "In addition, we found that RalA and RalB were labeled with anti-AG polyclonal antibody in myeloid leukemia cell lines by using 2D electrophoresis in conjunction with immunoblotting." (PMID 24587105, 2014).
oral squamous cell carcinoma (1 paper, 2022). "RalB has been implicated in several human cancers such as oral squamous cell carcinoma." (PMID 36613519, 2022).
ovarian carcinoma (1 paper, 2022). A malignant neoplasm originating from the surface ovarian epithelium. "Both RALA and RALB are highly upregulated in ovarian cancer cell lines." (PMID 35626682, 2022).
pheochromocytoma (1 paper, 2022). "The human RALA and RALB genes were cloned from a human pheochromocytoma cDNA library." (PMID 35409173, 2022).
prostate carcinoma (1 paper, 2022). A carcinoma that arises from epithelial cells of the prostate gland. "Several other investigations in prostate cancer have focused largely on RALA without complementary investigation of RALB." (PMID 35626682, 2022).
rectal cancer (1 paper, 2025). A primary or metastatic malignant neoplasm that affects the rectum. "Butyrate’s activation of OR51E1 promotes radiogenic autophagy in CRC cells, which correlates with increased RALB expression in clinical rectal cancer tissues and CRC mouse models." (PMID 40699664, 2025).
tumor (42 papers, 2009 to 2025). "Our analysis of BC patient tumor gene expression using the large METABRIC cohort found that elevated RALA expression was associated with poor outcomes while elevated RALB expression was associated with a more favorable prognosis." (PMID 39272901, 2024). "Activating RalA would promote the growth of tumor cells, and loss of RalB function inhibited tumor metastasis." (PMID 36499343, 2022). "Of the two mammalian Ral orthologs, RalA, is associated with tumor initiation and anchorage-independent growth, whereas RalB is associated with invasion, metastasis and survival." (PMID 34071831, 2021). "Expression of oncogenic alleles of KRAS induced cell death in TBK1-deficient murine embryonic fibroblasts, suggesting that RalB-Sec5-TBK1 controls a cell-autonomous host defense signaling pathway that inhibits tumor cell apoptosis." (PMID 30791439, 2019). "We have also shown that forced attachment of Ccnd1 to the membrane (caused by Ccdn1-CAAX expression) induces tumor cell invasiveness and metastasis in tumor cells through a RalB-dependent mechanism." (PMID 27105504, 2016). "Additionally, a Masson’s Trichrome stain of the MDA-MB-468 tumors suggests that loss of either RALA or RALB alters the collagen deposition, which is a phenotype associated with changes in BC tumor metabolism." (PMID 39272901, 2024). "Moreover, in vivo metastasis assays in mice (tail vein injection) and in hamsters (subcutaneous injection) supported a function of RalB pathway in the formation of tumor metastasis, both in Ras-mutated and Rous sarcoma virus-transformed cells." (PMID 30320548, 2018). "Depletion of either RALA or RALB significantly increased the tumor collagen area relative to shCTRL tumors." (PMID 39272901, 2024). "RALA knockout resulted in decreased Ki67 tumor staining while RALB knockout was accompanied by increased Ki67 staining." (PMID 39272901, 2024). "RALA and RALB adopt a plethora of roles in cancer, from supporting tumor growth to mediating invasion and metastasis." (PMID 39272901, 2024). "In cancer biology, evidence has highlighted the importance of the RALB/TBK1 pathway in cell autonomous survival by establishing a link between tumor formation and the innate immune response." (PMID 38519457, 2024). "Other work using stable shRNA-mediated RAL knockdown in 4T1 mouse BC cells identified RALB as a driver of primary tumor growth, while both RALs were reported to support lung metastasis in this model." (PMID 39272901, 2024). "As for in pancreatic cancers, RALA is essential for tumor growth, and RALA and RALB are both required for tumor invasion." (PMID 37250144, 2023). "Either paralog was sufficient to sustain tumor growth and only when both RALA and RALB were deleted was tumor formation blocked." (PMID 35626682, 2022). "Classically, different studies in human cells have shown that RalA is important for tumor cell growth, whereas RalB is important for tumor cell survival and invasiveness." (PMID 35897776, 2022). "In experiments utilizing PANC-1 cells, RALB was shown to be an important part of a multiprotein complex which drives tumor stemness and treatment resistance." (PMID 35626682, 2022). "RalB downregulation efficiently reduces tumor xenograft growth and diminishes proliferation in temozolomide-resistant GBM cells." (PMID 35897776, 2022). "The knockdown of RalB in GBM cells hinders the growth of a tumor mass in mouse-xenograft experiments." (PMID 35897776, 2022). "For instance, RalA is required for anchorage-independent proliferation, whereas RalB is indispensable for survival of tumour cells." (PMID 35879328, 2022). "This suggests RALA’s tumor and metastasis promoting functions predominate RALB’s tumor and metastasis-inhibiting activities." (PMID 34118960, 2021). "In pancreatic cancer, RALA and B have discrete roles with RALA supporting anchorage independent growth and tumor growth, while RALB is required for invasion and lung colonization." (PMID 34118960, 2021).
tumor (continued). "The activation of Ras small GTPases, including RalA and RalB, plays an important role in carcinogenesis, tumor progress, and metastasis." (PMID 34869198, 2021). "With this work, RalA and RalB add to the list of proteins known to control exosome secretion and to affect tumor progression, such as Rab27a, Alix, syntenin, and components of the ESCRT machinery." (PMID 33404012, 2021). "IHC staining of Ctrl, RALA-KO, and RALB-KO tumor sections for the apoptosis marker cleaved caspase 3 (CC3) revealed no significant changes across groups." (PMID 34118960, 2021). "CRISPR-mediated knockout of RALB significantly increased orthotopic TNBC tumor growth in vivo, increased 3D invasion, and increased cell viability in both adherent and nonadherent culture conditions." (PMID 34118960, 2021). "First, RalA and RalB have antagonist effects on tumor growth measured in vivo over time and ex vivo after 41 days: while RalA depletion significantly increased tumors growth, RalB depletion induced the opposite effect when compared to control tumors." (PMID 33404012, 2021). "Since on one hand RalA and RalB positively control the levels and the functionality of secreted tumor EVs, and on the other hand they promote metastasis, we tested a direct impact of RalA/B-dependent EVs on the promotion of lung metastasis." (PMID 33404012, 2021). "The necessity of RALA and RALB for TNBC tumor growth and metastasis were evaluated in vivo using orthotopic and tail-vein models." (PMID 34118960, 2021). "For example, a specific inhibitor of RALA and RALB was effective in reducing both cell proliferation and tumour growth in lung cancer xenografts." (PMID 34359657, 2021). "Analysis of RALB expression revealed higher RALB levels in tumour compared to the matched normal patient tissues." (PMID 33122623, 2020). "The active tivantinib as a single agent showed strong inhibition of various tumor-promoting signaling molecules, such as reduced RalB, CD44, c-Myc, and Id1 as well as inhibition of Akt activation, whereas the inactive enantiomer did not elicit much effect." (PMID 31100813, 2019). "RalGEF is a downstream effector of Ras that activates the Ras family proteins RalA and RalB, which are known to play a role in tumor growth and metastasis; RalA is involved in tumor initiation, whereas RalB is known to promote tumor metastasis." (PMID 31100813, 2019). "More interestingly, both RalB and RalA expression was higher in tumor cells than in normal juxtatumoral cells." (PMID 30320548, 2018). "The Ral (Ras-like) GTP-binding proteins (RalA and RalB), as effectors of the proto-oncogene Natural killer (NK) cells are an important component of the anti-tumor response." (PMID 25431955, 2014). "Here we compared the influence of constitutively active RalA and RalB expression on tumor progression." (PMID 21714887, 2011). "Earlier, it was suggested that RalA was essential for anchorage-independent growth of transformed cells while RalB was responsible for tumor cell-autonomous survival." (PMID 21714887, 2011). "We also presented here the data concerning effect of RalA and RalB on expression, phosphorylation status and activity of various key proteins known to be involved in tumor progression and metastasis." (PMID 21714887, 2011). "It was shown that RalA and RalB were necessary for acquisition of aggressive cellular phenotype in diverse models of tumor progression." (PMID 21714887, 2011). "Here we compared individual impact of RalA and RalB activation on stimulation of tumor growth and metastasis and estimated effect of simultaneous RalA and RalB overexpression on these properties." (PMID 21714887, 2011). "Other studies found that RALB is indispensable in tumor occurrence and progression." (PMID 41398523, 2025). "RALB regulates cell growth, tumor metastasis, and granule secretion." (PMID 41398523, 2025).